PDGFB (platelet derived growth factor subunit B)
Description:
Growth factor that plays an essential role in the regulation of embryonic development, cell proliferation, cell migration, survival and chemotaxis. Potent mitogen for cells of mesenchymal origin. Required for normal proliferation and recruitment of pericytes and vascular smooth muscle cells in the central nervous system, skin, lung, heart and placenta. Required for normal blood vessel development, and for normal development of kidney glomeruli. Plays an important role in wound healing. Signaling is modulated by the formation of heterodimers with PDGFA (By similarity).
Synonyms: PDGF2; SIS; SSV; IBGC5; PDGF-2; c-sis
Tractability: Antibody: its Gene Ontology location is reachable by antibodies, with high confidence; UniProt places it where antibodies can reach, with medium confidence; UniProt predicts a signal peptide or a membrane-spanning region. Other modalities: a drug acting on it is in phase 2 or 3 trials.
Target class: Secreted protein
Gene: Protein-coding gene on chromosome 22 (39,223,359 to 39,244,982, reverse strand). Ensembl gene ENSG00000100311.
Subcellular location: Secreted
Subcellular location (Human Protein Atlas): Vesicles; Predicted to be secreted
Pathways (Reactome):
Signal Transduction: Downstream signal transduction; PI5P, PP2A and IER3 Regulate PI3K/AKT Signaling; PIP3 activates AKT signaling; RAF/MAP kinase cascade; Signaling by PDGF
Disease: Constitutive Signaling by Aberrant PI3K in Cancer
Extracellular matrix organization: Non-integrin membrane-ECM interactions
Hemostasis: Platelet degranulation
Gene Ontology:
Molecular function: chemoattractant activity; collagen binding; growth factor activity; identical protein binding; platelet-derived growth factor binding; platelet-derived growth factor receptor binding; protein binding; protein heterodimerization activity; protein homodimerization activity; superoxide-generating NADPH oxidase activator activity; receptor ligand activity
Biological process: cell chemotaxis; cellular response to growth factor stimulus; cellular response to platelet-derived growth factor stimulus; gene expression; hemopoiesis; interleukin-18-mediated signaling pathway; intracellular signal transduction; monocyte chemotaxis; negative regulation of DNA-templated transcription; negative regulation of gene expression; negative regulation of miRNA transcription; negative regulation of phosphatidylinositol biosynthetic process; negative regulation of platelet activation; negative regulation of vascular associated smooth muscle cell differentiation; peptidyl-tyrosine phosphorylation; platelet-derived growth factor receptor signaling pathway; positive regulation of blood vessel endothelial cell migration; positive regulation of calcium ion import; positive regulation of cell migration; positive regulation of cell population proliferation; positive regulation of cell-substrate adhesion; positive regulation of chemotaxis; positive regulation of DNA biosynthetic process; positive regulation of DNA-templated transcription; positive regulation of endothelial cell proliferation; and 33 more
Cellular component: cell surface; extracellular matrix; platelet-derived growth factor complex; basolateral plasma membrane; cytoplasm; endoplasmic reticulum lumen; extracellular region; Golgi lumen; Golgi membrane; platelet alpha granule lumen; membrane
Genetic constraint (gnomAD): Loss-of-function variants: 6 observed, 25.05 expected, observed/expected ratio (o/e) 0.24, 90% interval 0.13 to 0.47. The upper end of that interval is the gene's LOEUF score, 0.47, which puts it in group 2 of 6, group 1 being the genes least tolerant of losing a copy. Missense variants: 299 observed, 340.84 expected, observed/expected ratio (o/e) 0.88, 90% interval 0.8 to 0.96. Synonymous variants: 144 observed, 139.97 expected, observed/expected ratio (o/e) 1.03, 90% interval 0.9 to 1.18.
Homologues: Orthologues: chimpanzee PDGFB (99% identical), pig PDGFB (93% identical), mouse Pdgfb (90% identical), guinea pig PDGFB (89% identical), rat Pdgfb (88% identical), macaque PDGFB (83% identical), rabbit PDGFB (83% identical), dog PDGFB (78% identical), tropical clawed frog pdgfb (46% identical), zebrafish pdgfbb (37% identical), zebrafish pdgfba (34% identical), Caenorhabditis elegans pvf-1 (22% identical), and 1 more. Paralogues in human: PDGFA (33% identical).
Diseases named in the same sentence as PDGFB in open-access papers:
PDGFB is named in the same sentence as 274 diseases in open-access papers, as found by Europe PMC text mining. Sharing a sentence is not in itself a finding about the gene and the disease. The quoted sentences say what the papers report.
glioma (114 papers, 2009 to 2025). A benign or malignant brain and spinal cord tumor that arises from glial cells (astrocytes, oligodendrocytes, ependymal cells). "To validate these findings in the context of human glioma, we obtained primary wtIDH glioma stem cells (GSCs), overexpressed PDGFB variants and performed immunoblotting of isolated cell fractions." (PMID 40060572, 2025). "In wild-type mice, glioma-like lesions resembling human glioblastoma, with massive necrotic areas were seen when recombinant Moloney murine leukemia virus encoding PDGFB was administered in combination with a replication-competent helper virus." (PMID 34199460, 2021). "To address the role of LRIG1 in PDGF-driven gliomas, we used the RCAS/Ntv-a system to induce glioma in mice with different Lrig1 genotypes via the intracranial transduction of neural progenitor cells with PDGFB-encoding RCAS viruses." (PMID 29391393, 2018). "Retroviral tagging using MMULV expressing PDGFB to identify novel glioma-causing genes gave one integration in NFIA, NFIB and NFIC each and five integrations in NFIX." (PMID 19337383, 2009). "As an example, genetic glioma models such as PDG-Ink4a, which is induced by RCAS-vectors encoding PDGFB in Nestin-Tv-a; Ink4a/Arf-/- transgenic mice, better recapitulate the mutational landscape of glioma patients compared to the chemically-induced GL261 glioma." (PMID 37954592, 2023). "Therefore, we assessed the composition of the glioma-associated microenvironment of treatment-naïve PDGFB-driven glioma in mice." (PMID 36358353, 2022). "Recently, it was found that Lrig2-deficient mice were protected against PDGFB-induced glioma." (PMID 25353163, 2014). "Therefore, we used an animal model of PDGF-induced glioma where PDGFB-encoding RCAS retroviruses are injected intracranially into Ntv-a transgenic mice." (PMID 24023893, 2013). "It has been well established that many macrophages have pro-tumorigenic effects in gliomas, and that the infiltration of these pro-tumorigenic macrophages, which are referred to as tumor-associated macrophages (TAMs), is partially driven by platelet-derived growth factor subunit B (PDGFB) signaling." (PMID 38523840, 2024). "In a PDGFB-driven glioma model, CSF-1R blockade inhibited tumor growth and improved mouse survival by re-programming GAMs rather than causing their depletion." (PMID 40642066, 2025). "Our studies suggest that a paracrine signaling loop exists in which mutant IDH inhibits chromatin binding of immune-derived PDGFB in glioma cells." (PMID 40060572, 2025). "To examine the nature of this putative relationship, we performed PDGFB ChIP-sequencing (ChIP-seq) on mouse and human glioma samples." (PMID 40060572, 2025). "Platelet-derived growth factor B (PDGFB) can drive formation of low-grade glioma and here we show that it localizes to the nucleus of human glioma cells where it binds chromatin to preserve genome stability and cell lineage." (PMID 40060572, 2025). "Given its correlation with poor survival outcomes and high expression levels in mIDH glioma, we sought to characterize PDGFB protein expression in mIDH tumors through immunostaining." (PMID 40060572, 2025). "Given that high PDGFB expression is associated with poor survival outcomes in mIDH glioma, we sought to define how mutations to IDH alter PDGFB-chromatin interactions and to discern the effects of these alterations on gliomagenesis and progression." (PMID 40060572, 2025).
glioma (continued). "To study the role of nuclear PDGFB in glioma progression, we developed a new model of immunocompetent glioma using in utero electroporation (IUE) of piggyBac transposase driving GFP and PDGFB overexpression (PDGFBwt) in neural progenitor cells." (PMID 40060572, 2025). "In glioma, increased production of PDGFB is attributed to expansion of the myeloid compartment, which is populated by tumor-infiltrating myeloid cells." (PMID 40060572, 2025). "These experimental results implicate immune cells as the origin of PDGFB in human glioma and demonstrate that a mammalian protein produced by one cell can translocate to the nucleus of a different cell." (PMID 40060572, 2025). "Immunoblotting of GSC cell fractions confirmed that PDGFB localized to the chromatin fraction, demonstrating that exogenous PDGFB can localize to the nucleus and bind chromatin in glioma cells bearing the cognate receptor, PDGFRA." (PMID 40060572, 2025). "Our studies identified high levels of PDGFB in human mIDH glioma and found PDGFB binds chromatin in human tumors." (PMID 40060572, 2025). "The results of these experiments confirmed that PDGFB binds chromatin in mIDH glioma, which is paralleled in our model of PDGFBwt mouse glioma." (PMID 40060572, 2025). "To gain a better understanding of the role of PDGFB in human glioma, we began with an examination of how PDGFB expression correlates with clinical outcome." (PMID 40060572, 2025). "To determine if PDGFB binds DNA, we performed chromatin immunoprecipitation (ChIP) on PDGFBwt induced mouse tumors (n=2) and surgically-resected human glioma samples (mIDH: n=7; wtIDH: n=5)." (PMID 40060572, 2025). "We used antibodies specific for the canonical IDH1R132H mutation and PDGFB to investigate the localization and distribution of PDGFB in mIDH glioma samples." (PMID 40060572, 2025). "Using RCAS/t-va murine models with PDGFb and BRAF V600E mutations, we identified distinct lncRNA signatures associated with the immunosuppressive and pro-inflammatory milieus of gliomas." (PMID 40527978, 2025). "Collectively, these studies show that immune derived PDGFB enters the nucleus of glioma cells to maintain genomic stability, while identifying a new mechanism by which IDH mutations promote gliomagenesis." (PMID 40060572, 2025). "Unexpectedly, we identified macrophages as the predominant source of PDGFB in human, finding that immune-derived PDGFB can localize to the nucleus of glioma cells." (PMID 40060572, 2025). "Immunostaining of IDH1R132H and PDGFB in mIDH glioma samples confirmed that cytoplasmic staining of PDGFB was absent from tumor cells but was detected in CD11b+ myeloid." (PMID 40060572, 2025). "These initial observations demonstrated that PDGFB expression is correlated with survival outcomes in mIDH glioma patients and is detected in the nuclei of cells in mIDH glioma." (PMID 40060572, 2025). "Collectively, these studies identify PDGFB as a novel chromatin-binding protein in mIDH glioma and describe a new immunocompetent model of low- to high-grade glioma." (PMID 40060572, 2025). "We developed a novel model of immunocompetent glioma, and found find that PDGFB normally translocates to the nucleus to bind the centromere." (PMID 40060572, 2025). "The expression of PDGFB in OPCs induced gliomas within distinct oligodendroglial (i.e. clear cell) appearance with an incidence of approximately 30%." (PMID 39324445, 2024). "In contrast, cultured PDGFb-driven RCAS glioma cells (≤ 7 passages) showed lower levels of GPNMB expression (n = 3, p = 0.3555) similar to astrocytes." (PMID 38566120, 2024). "Here, we integrated IL13RA2 into a construct encoding for PDGFB and used the RCAS/Tva system to develop a novel immunocompetent GEMM that both recapitulates diffuse midline gliomas and expresses the human glioma-associated antigen IL13RA2." (PMID 39711568, 2024).
glioma (continued). "Although IGFBP2 by itself does not result in cancer development, only one additional oncogenic event, such as K‐Ras or PDGFB induces gliomas." (PMID 39324445, 2024). "It has been observed in adult gliomas that PDGFB is highly overexpressed by macrophages and that its receptor PDGFRB is highly expressed by malignant cells." (PMID 38523840, 2024). "For example, in the p16Ink4a knockout RCAS PDGFB/Nestin-tvA glioma mouse model, the downregulation of PTPRD promoted cell proliferation, whereas restoring PTPRD expression in GBM cells resulted in the suppression of cell growth and the induction of apoptosis." (PMID 38339334, 2024). "In a mouse glioma model, high-grade glioma was developed in connection with intratumoral macrophages infiltration, in which mice PDGFB was expressed under the control of glioneuronal-specific nestin promoter." (PMID 37790751, 2023). "The genetically modified NSC lines were then orthotopically implanted into mice to generate PDGFB-driven, aggressive glioma tumors with high penetrance and short latency." (PMID 37760589, 2023). "For this analysis we used ZFTA-RELA gene fusion-driven ependymomas which are relatively large and cytologically distinct, whereas PDGFB-driven gliomas are more diffuse." (PMID 37739938, 2023). "In some tumors, such as glioma and ovarian cancer, PDGFB plays a crucial role in promoting angiogenesis and stimulating malignant cell proliferation." (PMID 36816016, 2023). "In their model, multifocal gliomas were first generated by injecting E14 embryos with replication-incompetent retroviral vectors expressing PDGFB in the lateral ventricles." (PMID 36765553, 2023). "Executed longitudinal MRI imaging of the PDGFB-driven glioma model revealed exponential growth kinetics of contrast-enhanced lesions." (PMID 36358353, 2022). "A late onset of BBB disruption and gadolinium-enhanced tumor visualization starting between days 25 and 27 emphasizes that appropriate therapy starting points in treatment studies are imperative for evaluating PDGFB-driven glioma." (PMID 36358353, 2022). "Taken together, we provided the multiparametric profiling of a PDGFB-driven glioma mouse model using the RCAS-tva delivery system and demonstrated radiological, histological, and metabolic features that are comparable to human high-grade glioma." (PMID 36358353, 2022). "Recurrent loss or other inactivation of PTPRD has been detected in different human malignancies, and one-copy loss of PTPRD has also been oncogenic in p16Ink4a knockout RCAS PDGFB/Nestin-tvA glioma mouse model." (PMID 35982066, 2022). "In contrast, the used PDGFB-driven glioma model offers the unique possibility to monitor the interval from tumor induction to the establishment of a clinically and biologically advanced tumor by close-meshed [18F]FET PET imaging time points." (PMID 36358353, 2022). "In contrast CD204, which was widely expressed in the syngeneic SMA560/VM-Dk model, showed a reduced frequency in the evaluated PDGFB-driven glioma." (PMID 36358353, 2022). "A platelet-derived growth factor B (PDGFB)-driven glioma model using the RCAS-tva system has been used to test a wide range of novel therapeutic targets." (PMID 36358353, 2022). "Here, we aimed at further characterizing the PDGFB-driven glioma model using the RCAS-tva delivery system, monitoring tumor growth dynamics as well as tumoral metabolic activity by neuroimaging." (PMID 36358353, 2022). "Therapy started only with a tumor volume of 40 mm3 in T2-weighted images, largely observed between weeks 4 and 5 after the tumor induction of PDGFB-driven glioma." (PMID 36358353, 2022). "In tumor cells, PDGFRA and PDGFA are commonly found and PDGFB and PDGFRB are expressed in glioma-linked endothelial cells." (PMID 34199460, 2021). "Even in vivo, DEXA was found to be anti-proliferative in PDGFB-driven gliomas, but to be pro-proliferative in GSC-derived orthotopic xenografts." (PMID 33478100, 2021).